DIAPH1 (diaphanous related formin 1)
Diseases named in the same sentence as DIAPH1 in open-access papers (continued):
Sharing a sentence is not in itself a finding about the gene and the disease.
cortical blindness (10 papers, 2021 to 2025). "At the same time, the loss of the DIAPH1 gene is associated with an autosomal recessive neurodevelopmental disorder known as seizures, cortical blindness, and microcephaly syndrome (SCBMS) alone or combined with immunodeficiency and mitochondrial dysfunction." (PMID 40981102, 2025). "Homozygous loss-of-function mutations in DIAPH1 are linked to a syndrome involving microcephaly, epilepsy, cortical blindness, and developmental delay, highlighting its importance in CNS development." (PMID 40981102, 2025). "In neurodegenerative contexts, observations of SCBMS (seizures, cortical blindness, microcephaly syndrome) suggest that DIAPH1 loss-of-function leads to progressive brain degeneration." (PMID 40981102, 2025). "Homozygote pathogenic variant in the DIAPH1 gene associated with Seizures, Cortical Blindness, and Microcephaly Syndrome (SCBMS)." (PMID 39578953, 2024). "Loss of function mutations in Diaphanous related formin 1 (DIAPH1) are associated with seizures, cortical blindness, and microcephaly syndrome (SCBMS) and are recently linked to combined immunodeficiency." (PMID 39120629, 2024). "Less than ten years ago, rare bi-allelic mutations in DIAPH1 were shown to cause an autosomal recessive disease called Seizures, Cortical blindness, and Microcephaly Syndrome (SCBMS)." (PMID 39076976, 2024). "Loss of function mutations (LoF) in DIAPH1 are associated with seizures, cortical blindness, and microcephaly syndrome (SCBMS)." (PMID 39120629, 2024). "Mutations in DIAPH1 results in mitochondrial dysfunction and immunodeficiency which can lead to seizures, cortical blindness, hearing loss and microcephaly syndrome." (PMID 36107978, 2022). "Whole exome sequencing (Illumina NovaSeq6000 platform; 100 bp reading length; paired-end sequencing) of peripheral blood DNA was requested, revealing a homozygous c.3145C > T variant in the DIAPH1 gene, reportedly associated with seizures, cortical blindness, and microcephaly." (PMID 36212620, 2022). "Biallelic mutations in DIAPH1 do not affect hearing function, but they have been causally linked with seizures, cortical blindness, and microcephaly syndrome (SCBMS, MIM #616632), a rare and severe autosomal recessive neurodevelopmental disorder." (PMID 35681420, 2022). "Accordingly, a recent publication reported additional patients with bi-allelic DIAPH1 mutations, and these patients displayed symptoms of combined immunodeficiency (CID) similar to those reported in LAT deficiency, in addition to microcephaly, seizures, cortical blindness, and developmental delay." (PMID 39076976, 2024).
microcephaly (10 papers, 2015 to 2025). A congenital or acquired developmental disorder in which the circumference of the head is smaller than normal for the person's age and sex. "The physiological role of RAGE-Diaph1 signaling also warrants investigation in the brain, as a homozygous mutation in Diaph1 has been associated with microcephaly, highlighting its critical role in early brain development." (PMID 41303665, 2025). "From this analysis, we identified a cohort of >30 patients with biallelic variants in DIAPH1 exhibiting clinical symptoms consistent with those exhibited by patient P1 i.e., microcephaly, intellectual disability, impaired vision and seizures." (PMID 40368919, 2025). "Bi-allelic mutations of DIAPH1 were first described in patients with a severe neurological phenotype including microcephaly, intellectual disability, seizures, and blindness." (PMID 39076976, 2024). "Lastly, a nonsense mutation of the formin related DIAPH1 (human mDia1) in humans has been found to cause microcephaly." (PMID 25883548, 2015). "The affected children in these families had homozygous DIAPH1 mutations F923fs/F923fs and R1049X/R1049X, respectively, and were diagnosed with postnatal microcephaly, early-onset epilepsy, severe visual impairment, and pulmonary symptoms including bronchiectasis and recurrent respiratory infections." (PMID 39076976, 2024). "DIAPH1 plays a crucial role in human brain development and is linked to microcephaly." (PMID 36310845, 2022). "The syndromes or intellectual developmental disorders caused by variants in DIAPH1, AFF2, BCORL1 and BRWD3 are occasionally with abnormalities of cranium, such as microcephaly or macrocephaly tall forehead." (PMID 36118902, 2022). "Similar to other cases of DIAPH1 deficiency, this patient had non-hematological phenotypes including microcephaly, developmental delay, and impaired vision." (PMID 39076976, 2024). "In support of this hypothesis, it was reported that the Diaph1 knock-out mice did not recapitulate the microcephaly phenotype described in humans with the DIAPH1 homozygous truncating mutation." (PMID 36689403, 2023).
Immunodeficiency (9 papers, 2022 to 2025). Failure of the immune system to protect the body adequately from infection, due to the absence or insufficiency of some component process or substance. "A homozygous autosomal recessive pathogenic variant in DIAPH1 has been detected in an Iranian boy with microcephaly syndrome and immunodeficiency." (PMID 39578953, 2024). "More recently, investigations of additional patients with bi-allelic DIAPH1 mutations have shown that the phenotype of this rare monogenic disease features prominent and potentially fatal immune deficiency and dysregulation, in addition to the previously recognized SCBMS phenotypes." (PMID 39076976, 2024). "A recent study showed that loss of DIAPH1 causes immunodeficiency." (PMID 36589226, 2022). "Approximately a third of affected individuals developed recurrent infections indicating that whilst clinical immunodeficiency is commonly associated with DIAPH1 dysfunction, it is not ubiquitously observed in all patients." (PMID 40368919, 2025). "Such a defect has previously been shown in animal models, so immunodeficiency can be expected in such patients given the functions of DIAPH1 in actin nucleation and microtubule organization and considering that mutations in several cytoskeleton-regulating genes cause primary immunodeficiency." (PMID 36212620, 2022). "Furthermore, aspergillosis is yet to be reported in patients with homozygous DIAPH1 loss, and the link between SCBMS and immunodeficiency remains elusive." (PMID 36212620, 2022).
breast carcinoma (8 papers, 2016 to 2023). "To further confirm the presence of IDR in the protein regions encoded by breast-cancer-associated AS events, we analyzed ADD3, PACSIN2, DIAPH1, MARK3, and MAP3K7 protein sequences with the PONDR web tool, a predictor of natural disordered regions." (PMID 34202984, 2021). "DIAPH1 has been reported to be involved in the progression of many types of tumors, such as breast cancer, colorectal cancer, and malignant glioma." (PMID 34631544, 2021). "Examples of this function are DIAPH1-3 and DAAM1 in breast cancer, DIAPH1 in glioma, FMNL1 in nasopharyngeal carcinoma, FMNL2 in colorectal cancer, and FHOD1 in oral squamous carcinoma." (PMID 34685534, 2021). "Consistent with the DIAPH1 expression patterns observed in glioma, colorectal and breast cancers, and oral squamous cell carcinoma, IHC and western blotting of paired LSCC and ANT tissues showed that DIAH1 was overexpressed in LSCC." (PMID 30733838, 2019). "DIAPH1 downregulation was reported to suppress invasion and/or migration in breast cancer, colon cancer, and glioblastoma." (PMID 31861134, 2019). "Finally, in our functional analysis of aberrantly expressed AS exons in breast cancer cells and tissues (PACSIN2 exon 8, DIAPH1 exon 2, MARK3 exon 16, ADD3 exon 13, and MAP3K7 exon 12), we found that dysregulated cassette exons encode for IDRs." (PMID 34202984, 2021). "Importantly, we were also able to confirm, by RT-PCR, the aberrant AS regulation of PACSIN2, DIAPH1, MARK3, ADD3, MAP3K7, and MARK2 in RNA extracts from two human tumor breast cancer samples tissues and two non-pathological tissues." (PMID 34202984, 2021).
atherosclerosis (7 papers, 2022 to 2025). A disease characterized by the build-up of fatty material and calcium deposition in the arterial wall resulting in partial or complete occlusion of the arterial lumen. "Male and female mice deficient in DIAPH1 are protected from the development of experimental atherosclerosis and display reduced cholesterol levels; these changes are linked to the regulation of SREBP1 subcellular localization." (PMID 36932214, 2023). "To begin to account for the mechanisms underlying these differences in atherosclerosis upon global deletion of Diaph1, we performed studies to determine the state of inflammation in these mice." (PMID 36932214, 2023). "Through multiple experimental strategies, this work identified that deletion of Diaph1 in atherosclerosis-prone mice protected from progression of atherosclerosis and uncovered unanticipated roles for DIAPH1 in the regulation of lipid metabolism." (PMID 36932214, 2023). "To explore potential roles for DIAPH1 in the progression of atherosclerosis, we began by probing expression of DIAPH1 in atherosclerosis." (PMID 36932214, 2023). "As RAGE has been extensively studied in atherosclerosis, here we sought to test potential roles for DIAPH1 in vascular pathology." (PMID 36932214, 2023). "In the sections to follow, recent work highlighting new insights into RAGE/DIAPH1 and atherosclerosis are detailed." (PMID 35562970, 2022). "Upon development of atherosclerosis, aortic arches were surgically interpositioned into the vasculature of the recipient diabetic wild-type, Ager null or Diaph1 null mice." (PMID 35811725, 2022). "This work unveils new regulators of atherosclerosis and lipid metabolism through DIAPH1." (PMID 36932214, 2023). "Previous work implicating the receptor for advanced glycation end products (RAGE) in atherosclerosis prompted us to explore if Diaphanous 1 (DIAPH1), which binds to the RAGE cytoplasmic domain and is important for RAGE signaling, contributes to these processes." (PMID 36932214, 2023).
atherosclerosis (continued). "On account of the evidence linking DIAPH1 to atherosclerosis through lipid metabolism, we examined potential signaling pathways by which DIAPH1 might regulate nuclear translocation of SREBP1, SREBP2 and ChREBP in the livers of the mice under study." (PMID 36932214, 2023). "Such experiments, coupled with single cell/single nucleus transcriptomic studies, may distinguish the effects of DIAPH1 in vascular cells, immune cells or hepatocytes and their cross-talk on lipid metabolism, inflammation and atherosclerosis." (PMID 36932214, 2023). "To provide further insight into the question of whether DIAPH1-dependent roles in atherosclerosis were mediated through regulation of lipid vs. glucose/carbohydrate or insulin metabolism, we performed a series of correlation analyses." (PMID 36932214, 2023). "Compared to wild-type diabetic recipient mice, diabetic mice devoid of Ager or Diaph1 displayed accelerated regression of atherosclerosis with smaller atherosclerotic lesion areas, reduced lesional neutral lipid staining (Oil Red O) and reduced macrophage content per lesion area (CD68+ cells)." (PMID 35811725, 2022). "Collectively, the results of the present studies buttress the connections between RAGE and DIAPH1 and suggest that blockade of RAGE/DIAPH1 may be a key adjunctive strategy in therapeutic approaches to atherosclerosis, at least in part through regulation of lipid metabolism." (PMID 36932214, 2023). "Although these mice were diabetic and did not have atherosclerosis, these findings nevertheless suggested that DIAPH1 might contribute to regulation of lipid metabolism; the underlying mechanisms or direct effects on atherosclerosis were not explored in that study." (PMID 36932214, 2023). "Although this review detailed roles for this axis in macrovascular atherosclerosis and microvascular diabetic kidney disease, RAGE/DIAPH1 has been shown to play damaging roles in other tissues vulnerable to complications as well." (PMID 35562970, 2022).
glioma (7 papers, 2015 to 2024). A benign or malignant brain and spinal cord tumor that arises from glial cells (astrocytes, oligodendrocytes, ependymal cells). "Several studies have demonstrated that DIAPH1 controls the metastatic capacity of colon carcinoma and glioma cells." (PMID 36589226, 2022). "Knockdown of DIAPH1 also inhibits the migration of human glioma cells." (PMID 36589226, 2022). "For example, Diaph1 knockdown suppress migration and reduces the expression of matrix metallopeptidase MMP2 and MMP9 in human glioma cells." (PMID 39010074, 2024).
melanoma (7 papers, 2009 to 2024). A malignant, usually aggressive tumor composed of atypical, neoplastic melanocytes. "Mass spectrometry combined with a visual screen has shown that in melanoma M2 cells, the cortex is nucleated predominantly by the formin mDia1 (encoded by DIAPH1) and the Arp2/3 complex." (PMID 30026344, 2018). "High MITF levels are thought to promote cell proliferation through the direct activation of the DIAPH1 gene, and low MITF expression in melanoma is associated with cell migration." (PMID 36248850, 2022). "Regulation of the DIAPH1 gene is important in regulating the transcription factor Mitf, which in turn regulates the invasiveness of melanoma." (PMID 19208118, 2009). "At the transcriptional level, MITF controls genes involved in cell survival (BCL2, HIF1A, BCL2A1), migration (DIAPH1, MET) and proliferation (CDK2, TBX2, CDKN1B), providing important signals for growth of melanoma cells." (PMID 34289891, 2021). "On the other hand, MITF directly binds to the promoter region of diaphanous homolog 1 (DIAPH1, DIA1) gene and activates its transcription, resulting in inhibiting the invasiveness of melanoma by activation of actin polymerization." (PMID 22046555, 2011).
myelodysplastic syndrome (7 papers, 2009 to 2025). A clonal hematopoietic disorder characterized by dysplasia and ineffective hematopoiesis in one or more of the hematopoietic cell lines. "Loss of DIAPH1, which encodes mDia1 protein, is associated with myelodysplastic syndrome and defects in T cell and neutrophil trafficking/polarization." (PMID 24587343, 2014). "The DIAPH1 gene encoding human mDia1 (located at 5q31.3) lies between the two commonly deleted regions mapped by conventional cytogenetics in myelodysplastic syndrome (MDS) patient samples." (PMID 19768111, 2009).
Obesity (6 papers, 2020 to 2025). Accumulation of substantial excess body fat. "There is growing experimental evidence supporting a link between AGE/RAGE/DIAPH1 and the pathophysiology of obesity and associated metabolic disorders." (PMID 34103691, 2021). "If the expression of GLO1/RAGE/DIAPH1 in adipose tissue is altered by increasing degrees of obesity and whether the expression of these genes associates with adipose tissue inflammation and adipocyte metabolism markers was addressed in the present studies." (PMID 34103691, 2021). "In fact, higher RAGE and Diaph1 expression in subcutaneous fat was linked to worse insulin sensitivity, underscoring an “immunometabolic” role of the AGE/RAGE/Diaph1 axis in human obesity-related insulin resistance." (PMID 40981102, 2025). "Nevertheless, our novel observations highlight a role for the AGE/RAGE/DIAPH1 axis in the pathophysiology of obesity and IR." (PMID 34103691, 2021). "Therefore, the elevated plasma DIAPH1 levels in OW women suggest a threat of hyperglycemia and obesity." (PMID 35185386, 2022). "Finally, recent work has addressed the potential relationships between AGER and DIAPH1 expression and metabolic health in patients with obesity." (PMID 35811725, 2022). "Taken together, these data suggest a potential dichotomy whereby expression of genes in the AGE/RAGE/DIAPH1 axis is closely associated with each other in SAT but not OAT in obesity, while inflammatory genes associate with each other in OAT but not SAT." (PMID 34103691, 2021). "We also sought to determine if the AGE/RAGE/DIAPH1 axis is linked to markers of adipogenesis (PPARG & PPARGC1A) and metabolic genes that we previously identified to be regulated by RAGE in a mouse model of obesity (UCP1 and CIDEA)." (PMID 34103691, 2021). "While absolute expression of genes in the AGE/RAGE/DIAPH1 axis in the surveyed adipose depots was unaltered by the degree of obesity, expression of genes in this axis strongly and positively correlated with markers of adipogenesis and inflammation, an effect that was more pronounced in SAT than OAT." (PMID 34103691, 2021). "Thus, we conclude that with the exception of the gene encoding PGC1α, genes in the AGE/AGER/DIAPH1 axis, inflammatory and adipocyte metabolism markers are not differentially regulated by the degree of obesity among obese subjects." (PMID 34103691, 2021). "Diaphanous related formin 1 (DIAPH1) is a novel component of advanced glycation end product (AGE) signal transduction that was recently found to participate in diabetes-related disorders, obesity, and androgen hormones." (PMID 35185386, 2022). "Diaph1 may be crucial in obesity and lipid disorders, but our results do not confirm its therapeutic potential in DPN." (PMID 41148850, 2025). "Altogether, these observations support and add to a repertoire of studies implicating RAGE as a key immunometabolic player in human obesity and open the possibility that common transcription factors may be regulating the genes in the AGE/RAGE/DIAPH1 axis, inflammation and adipose metabolism." (PMID 34103691, 2021). "While it remains unknown whether or not DIAPH1 plays a central role in regulation of adipose tissue biology, obesity and IR, ongoing studies in our laboratory suggest that DIAPH1 is a key contributor to obesity." (PMID 34103691, 2021).